TUG1 (taurine up-regulated 1)
Diseases named in the same sentence as TUG1 in open-access papers (continued):
Sharing a sentence is not in itself a finding about the gene and the disease.
lung neoplasm (2 papers, 2022 to 2023). A benign or malignant, primary or metastatic neoplasm involving the lungs. "More importantly, we predict that lncRNA taurine-upregulated gene 1 (TUG1) may be associated with lung neoplasms." (PMID 35938010, 2022). "A recent report found that TUG1 is among the most expressed LncRNAs in LC and may be a biomarker of lung neoplasms." (PMID 37928877, 2023). "In this section, we infer that TUG1 may be the biomarker of lung neoplasms." (PMID 35938010, 2022). "We predict that TUG1, PTENP1, and UCA1 may be the biomarkers of lung neoplasms, NSCLC and LUAD, respectively." (PMID 35938010, 2022).
metastatic disease (2 papers, 2016 to 2017). "Age at initial pathologic diagnosis, tumor size (T1 to T4), involvement of lymph nodes (N0 to N3), and presence of metastatic disease (M0 or M1) were considered as covariates, along with TUG1 expression." (PMID 29657297, 2017).
myocardial ischemia (2 papers, 2021 to 2022). A disorder of cardiac function caused by insufficient blood flow to the muscle tissue of the heart. "TUG1 has a wide range of regulatory functions and is widely recognized in the tumor field to promote proliferation, migration, cell cycle changes and inhibit apoptosis, whereas upregulation of TUG1 in myocardial ischemia/reperfusion (MI/R) injury is thought to promote apoptosis." (PMID 36581789, 2022).
schizophrenia (2 papers, 2021 to 2025). A major psychotic disorder characterized by abnormalities in the perception or expression of reality. "While Gomafu, PINT, GAS5, TCONS_l2_00021339, IFNG-AS1, FAS-AS1, PVT1, and TUG1 are among down-regulated lncRNAs in schizophrenia, MEG3, THRIL, HOXA-AS2, Linc-ROR, SPRY4-IT1, UCA1, and MALAT1 have been up-regulated in these patients." (PMID 34220567, 2021). "We have recently demonstrated down-regulation of FAS-AS1, PVT1, and TUG1 in patients with schizophrenia compared with controls." (PMID 34220567, 2021).
tongue squamous cell carcinoma (2 papers, 2020 to 2021). A squamous cell carcinoma that arises from the tongue. "Down-regulation of lncRNA TUG1 inhibited cisplatin resistance in drug-resistant tongue squamous cell carcinoma cells, by mediating miR-133b and cysteine-X-cysteine chemokine receptor 4 (CXCR4)." (PMID 34039257, 2021). "In tongue squamous cell carcinoma, down-regulation of lncRNA TUG1 inhibited cell proliferation, and silencing of lncRNA TUG1 regulated the progression of the cell cycle." (PMID 34039257, 2021). "However, little is known about the role of TUG1 in drug resistance and its mechanism in tongue squamous cell carcinoma (TSCC)." (PMID 32390763, 2020).
triple-negative breast carcinoma (2 papers, 2018 to 2020). An invasive breast carcinoma which is negative for expression of estrogen receptor (ER), progesterone receptor (PR), and human epidermal growth factor receptor 2 (HER2). "On the contrary, TUG1 expression was down-regulated in triple negative breast cancer, and overexpression of TUG1 enhance DDP sensitivity in MDA-MB-231 and BT549 cells by sponging miR-197." (PMID 30519392, 2018).
type 2 diabetes (2 papers, 2020 to 2022). "We also validated that podocytes isolated from kidneys of leptin receptor-deficient (db/db) mice, an established model of type 2 diabetes, exhibited significant downregulation of Tug1 expression compared with podocytes obtained from control nondiabetic (db/m) mice." (PMID 32467232, 2020).
ulcerative colitis (2 papers, 2021 to 2026). An inflammatory bowel disease involving the mucosal surface of the large intestine and rectum. "In another ulcerative colitis murine model, TUG1 suppressed intestinal epithelial cell apoptosis, thereby inhibited the progression of ulcerative colitis." (PMID 34630395, 2021).
urothelial carcinoma (2 papers, 2017). A malignant neoplasm derived from the transitional epithelium of the urinary tract (urinary bladder, ureter, urethra, or renal pelvis).
vitiligo (2 papers, 2021 to 2024). Generalized well circumscribed patches of leukoderma that are generally distributed over symmetric body locations and is due to autoimmune destruction of melanocytes. "In vitiligo patients, the expression of the lncRNA Taurine-upregulated gene 1 (TUG1) was found to be decreased compared to healthy controls." (PMID 39735711, 2024).
acute lung injury (1 paper, 2020). A condition of lung damage that is characterized by bilateral pulmonary infiltrates (pulmonary edema) rich in neutrophils, and in the absence of clinical heart failure. "Many studies have indicated that TUG1 is downregulated in lung-related diseases, including acute lung injury (ALI) and non-small cell lung cancer (NSCLC)." (PMID 33194901, 2020).
adenomyosis (1 paper, 2025). The growth of endometrial tissue inside the muscular wall of the uterine corpus. "However, both conditions show dysregulation of EZH2-mediated chromatin silencing—via lncRNAs like TUG1 in adenomyosis and DALI in fibroids —suggesting that epigenetic control of smooth muscle identity may be a shared vulnerability." (PMID 41226749, 2025).
adenovirus infection (1 paper, 2022). "To study the function of TUG1 in HepG2 development in vivo, we inoculated mice with HepG2 and administered exosomes derived from CAFs with or without TUG1 shRNA adenovirus infection to tumor-bearing mice." (PMID 35193488, 2022).
age (1 paper, 2021). A temporal measurement of the time period elapsed since an identifiable point in the life cycle of an organism. "Moreover, lncRNA TUG1 enhanced apoptosis of lens epithelial cells by modulating the miR-421/caspase-3 network in age-related cataract." (PMID 34517787, 2021).
aortic valve disease (1 paper, 2022). "Existing studies have demonstrated that, TUG1, high expression in calcified aortic valve disease, can play a role of sponge to adsorb miR-204-5p, up-regulate Runx2 expression, and promote osteoblastic differentiation in CAVD." (PMID 35358011, 2022).
Arthritis (1 paper, 2023). Inflammation of a joint. "Moreover, the results reflected that TUG1 gene polymorphism was associated with prolonged disease duration and unfavorable clinical laboratory parameters, such as more arthritis, renal affection, leucopenia and thrombocytopenia, higher CRP, ESR, C3, and C4 levels, and a higher percentage of dsDNA." (PMID 37736902, 2023).
Ataxia (1 paper, 2024). Ataxia refers to impaired coordination of voluntary muscle movement. "It is important to note that our findings rule out the confounding influence of dox treatment in FRDAkd mice, strengthening Tug1’s candidacy as a Friedreich's ataxia-specific biomarker." (PMID 38846537, 2024).
Azoospermia (1 paper, 2020). Absence of any measurable level of sperm,whereby spermatozoa cannot be observed even after centrifugation of the semen pellet. "Although Tug1−/− males produce fewer sperm, none was found to completely lack sperm (a condition called azoospermia)." (PMID 32894169, 2020).
central nervous system leukemia (1 paper, 2021). Leukemia infiltrating the central nervous system structures. "Further analysis indicated that in Ph− ALL patients, higher lncRNA TUG1 tier was correlated with the presence of central nervous system leukemia, increased white blood cell level, and bone marrow blasts." (PMID 34251066, 2021).
cerebral infarction (1 paper, 2022). An ischemic condition of the brain, producing a persistent focal neurological deficit in the area of distribution of the cerebral arteries. "To summarize, our study indicates that TUG1 inhibited angiogenesis following cerebral infarction by negatively modulating the expression of VEGF through sponging miR-26a." (PMID 36330459, 2022). "The relative level of TUG1 and miR-26a in samples after cerebral infarction was detected by qRT-PCR." (PMID 36330459, 2022). "Earlier researches suggested that TUG1 may have a vital role in the pathological changes after cerebral infarction." (PMID 36330459, 2022). "Further researches revealed that TUG1 could effectively downregulate the expression of miR-26a and abolish the promoting role of miR-26a in angiogenesis following cerebral infarction." (PMID 36330459, 2022). "However, the role and mechanism of TUG1 on angiogenesis following cerebral infarction remain hazy." (PMID 36330459, 2022).
childhood asthma (1 paper, 2021). "Moreover, we examined TUG1, miR-216a-3p and SMURF2 expression in blood samples of patients with childhood asthma and PDGF-BB-stimulated HASMCs." (PMID 34749662, 2021).
chronic asthma (1 paper, 2025). An asthma that is characterized by the development of persistent airway inflammation and recurrent attacks of breathlessness and wheezing, which vary in severity and frequency. "In parallel, Wang and Chen found that lncRNA TUG1 promotes the proliferation and migration of airway smooth muscle cells (ASMCs) through the regulation of the miR-216a-3p/SMURF2 axis, linking it to structural airway changes seen in chronic asthma." (PMID 40806181, 2025).
chronic obstructive pulmonary disease (1 paper, 2020). A chronic and progressive lung disorder characterized by the loss of elasticity of the bronchial tree and the air sacs, destruction of the air sacs wall, thickening of the bronchial wall, and mucous accumulation in the bronchial tree. "Growing literature has indicated that dysregulation of TUG1 is involved in lung-related diseases, such as chronic obstructive pulmonary disease (COPD), pneumonia, and pulmonary arterial hypertension (PAH)." (PMID 33194901, 2020).
Cognitive impairment (1 paper, 2020). Abnormal cognition is characterized by deficits in thinking, reasoning, or remembering. "Meanwhile, the overexpression of TUG1 reversed the therapeutic effects of aerobic exercise on cognitive impairment." (PMID 33213523, 2020). "Finally, we demonstrated that aerobic exercise can improve cognitive impairment and inhibit hippocampal apoptosis of VCI mice by downregulating TUG1 expression." (PMID 33213523, 2020).
Ewing sarcoma (1 paper, 2021). A small round cell tumor that lacks morphologic, immunohistochemical, and electron microscopic evidence of neuroectodermal differentiation. "In Ewing’s sarcoma, the target regulatory interaction between miR-199a-3p and TUG1 is confirmed." (PMID 34787069, 2021).
experimental autoimmune encephalomyelitis (1 paper, 2022). An autoimmune demyelinating disease of the central nervous system that is produced experimentally in animals by the injection of homogenized brain or spinal cord in Freund's adjuvant. "In experimental autoimmune encephalomyelitis (EAE) mice and lipopolysaccharide-induced BV2 cells, Yue and colleagues discovered that down-regulation of TUG1 attenuates MS through the inhibition of inflammation by sponging miR-9-5p via targeting NF-κB1/p50." (PMID 36324503, 2022).
Friedreich ataxia (1 paper, 2024). An inherited condition that affects the nervous system and causes movement problems. "To validate this, we manually selected the top 16 Tug1 targets based on differential expression P-value, expression in multiple tissues and association with cellular processes affected in Friedreich's ataxia as evidenced by the literature." (PMID 38846537, 2024). "In additional human samples, TUG1 levels were significantly downregulated in both whole blood and serum of Friedreich’s ataxia patients compared with controls (Wilcoxon signed-rank test, P < 0.05)." (PMID 38846537, 2024). "By analysing genomics data from both human and mouse models, we detected reduced expression of TUG1 in Friedreich's ataxia." (PMID 38846537, 2024). "We also examined and quantified the whole-blood TUG1 expression levels between age- and sex-matched Friedreich's ataxia patients (n = 72) and heterozygous carriers (n = 66)." (PMID 38846537, 2024). "In this study, we focus on the long non-coding RNA (lncRNA) taurine-upregulated gene 1 (TUG1) as a prospective biomarker for Friedreich's ataxia." (PMID 38846537, 2024). "We observed varying expressions of Tug1 targets across different tissues, indicative of Tug1's multifaceted roles in Friedreich's ataxia." (PMID 38846537, 2024). "The results show a notable downregulation of TUG1 in both whole blood and serum of Friedreich's ataxia patients." (PMID 38846537, 2024). "Our comparative evaluation focused on whole-blood TUG1 expression levels across age- and sex-matched individuals, including Friedreich's ataxia patients (n = 72), heterozygous carriers (n = 68) and healthy controls (n = 43)." (PMID 38846537, 2024). "The differential expression of Tug1 and Slc40a1 in intracardiac blood positions these genes as exemplary candidate biomarkers for Friedreich's ataxia, particularly appealing due to the minimal invasiveness required for patient sample collection." (PMID 38846537, 2024). "This novel understanding not only underscores the potential of TUG1 as a therapeutic target but also lays the groundwork for subsequent investigations into the molecular pathways modulated by TUG1 in Friedreich's ataxia." (PMID 38846537, 2024). "This study proposes TUG1, a long non-coding RNA, as a promising blood-based biomarker for Friedreich’s ataxia, which is known to regulate various cellular processes." (PMID 38846537, 2024). "TUG1 holds potential for Friedreich’s ataxia monitoring and therapeutic development, meriting additional research." (PMID 38846537, 2024). "In summary, our thorough examination of TUG1 expression levels across multiple cohorts and experimental frameworks has unveiled a distinct gene expression profile in Friedreich's ataxia patients." (PMID 38846537, 2024). "To investigate TUG1 expression levels in patients with Friedreich's ataxia, we analysed the publicly available microarray data set GSE102008." (PMID 38846537, 2024). "The results collectively demonstrated a marked downregulation of TUG1 expression in both whole blood and serum from Friedreich's ataxia patients." (PMID 38846537, 2024). "In conclusion, our rigorous study underscores TUG1's critical role as a prospective blood-based biomarker for Friedreich's ataxia." (PMID 38846537, 2024). "Utilizing a robust methodology and in-depth analyses, we have confirmed the functional importance of Tug1 and its downstream targets in tissues specific to Friedreich's ataxia." (PMID 38846537, 2024). "This intricate involvement of TUG1 in Friedreich's ataxia's neurodegenerative pathology underscores its multifaceted role, emphasizing the need for further exploration of its potential as a biomarker across various stages of the disease." (PMID 38846537, 2024). "This is based on Tug1's consistent expression across various tissues and patient samples, making it a reliable biomarker for Friedreich's ataxia." (PMID 38846537, 2024).
Friedreich ataxia (continued). "In the context of these findings, Tug1 emerged as a more suitable biomarker for Friedreich's ataxia compared with Slc40a1." (PMID 38846537, 2024). "Tug1 and Slc40a1 emerged as potential blood-based biomarkers, confirmed in the Friedreich’s ataxia knockdown mouse model (one-way ANOVA, P ≤ 0.05)." (PMID 38846537, 2024). "This suggests TUG1's utility as an early, non-invasive blood-based biomarker for Friedreich's ataxia, with potential implications for disease monitoring and therapeutic development." (PMID 38846537, 2024). "This emphasizes Tug1's potential as a highly specific biomarker for Friedreich's ataxia." (PMID 38846537, 2024). "This study identifies TUG1 as a potential blood-based biomarker for Friedreich’s ataxia, showing consistent expression variance in human and mouse tissues related to disease severity and key Friedreich’s ataxia pathways." (PMID 38846537, 2024). "Our analysis of serum samples from 45 patient serum and 45 healthy control serum samples showed a significant downregulation of serum TUG1 expression levels in Friedreich's ataxia patients compared with healthy controls, as confirmed through RT-qPCR, employing the Wilcoxon signed-rank test." (PMID 38846537, 2024). "For instance, Nedd1, a gene involved in cellular senescence, exhibited significant downregulation in multiple tissues in FRDAkd mice, reinforcing the vital role Tug1 may play in the cellular biology disrupted in Friedreich's ataxia." (PMID 38846537, 2024). "Furthermore, TUG1 exhibits a complex relationship with both age of onset and disease duration in Friedreich's ataxia, indicating its diverse roles across different disease stages." (PMID 38846537, 2024). "Insights into the molecular pathways of TUG1 could lead to targeted therapies, transforming Friedreich's ataxia drug development." (PMID 38846537, 2024). "Subsequently, to uncover the functional relevance of TUG1 expression, we constructed a correlation heat map that revealed the relationship between blood TUG1 expression levels (fold-change) and various demographic and clinical characteristics of Friedreich's ataxia patients." (PMID 38846537, 2024). "In summary, these experiments reveal a consistent expression pattern of Tug1 in response to Fxn knockdown and restoration, highlighting its significant downregulation across various tissues and its potential role as a specific biomarker for Friedreich's ataxia." (PMID 38846537, 2024). "Given the evidence indicating significant correlations between TUG1 fold-change and various factors including disease onset, duration and the FDS score in Friedreich's ataxia, we further explored these relationships through linear regression analyses." (PMID 38846537, 2024).
glaucoma (1 paper, 2023). Increased pressure in the eyeball due to obstruction of the outflow of aqueous humor. "LncRNA TUG1, originating from the TUG1 gene (Section 5.3), has been shown to be downregulated in a glaucoma mice model subjected to an ischemic reperfusion and in a H2O2-treated mouse retinal ganglion cell line." (PMID 36768958, 2023). "Furthermore, downregulation of TUG1 was detected in a glaucoma mouse model, whereas its upregulation relieved the severity of the retinal injury." (PMID 36768958, 2023).
hemangioma (1 paper, 2021). A benign vascular lesion characterized by the formation of capillary-sized or cavernous vascular channels. "Spearman’s correlation analysis indicated that TUG1 levels were negatively correlated to miR-137 levels in infant hemangioma tissues (p < 0.05, R2 = 0.1806)." (PMID 34362467, 2021). "In the present study, we found that TUG1 was significantly upregulated in infant hemangioma tissues, especially in proliferating-phase hemangioma tissues." (PMID 34362467, 2021). "TUG1 was significantly upregulated in infant hemangioma tissues compared with normal adjacent subcutaneous tissues." (PMID 34362467, 2021). "Two short hairpin RNA targeting TUG1 (sh-TUG1-1 and sh-TUG1-2) were transfected into hemangioma-derived endothelial cells, HemECs, to block its expression." (PMID 34362467, 2021). "The results showed that TUG1 was upregulated in IH tissues, especially in the proliferative-phase hemangioma tissues." (PMID 34362467, 2021). "In addition, TUG1 expression was significantly higher in the proliferating-phase hemangioma tissues than in the involuting-phase hemangioma tissues (p < 0.01)." (PMID 34362467, 2021).
Hepatitis (1 paper, 2020). Inflammation of the liver. "Our data revealed that deletion of TUG1 protected against LPS-induced hepatocyte inflammation via regulating miR-140/TNF, which might provide new insight for hepatitis treatment." (PMID 33644034, 2020).
hypertensive nephropathy (1 paper, 2025). Kidney damage that results from chronically elevated blood pressure; complications include glomerular damage resulting in proteinuria and hematuria. "A ceRNA regulatory network directly associated with hypertensive nephropathy was established, and the insulin signaling pathway was identified as directly linked to hypertensive nephropathy, modulated by lncRNAs SNHG14, TUG1, ZNF252P-AS1, and MIR503HG." (PMID 40083322, 2025).